MXRA5 (matrix remodeling associated 5)
Description:
In kidney, has anti-inflammatory and anti-fibrotic properties by limiting the induction of chemokines, fibronectin and collagen expression in response to TGB1 and pro-inflammatory stimuli.
Synonyms: DKFZp564I1922
Tractability: Antibody: UniProt places it where antibodies can reach, with high confidence; UniProt predicts a signal peptide or a membrane-spanning region; its Gene Ontology location is reachable by antibodies, with medium confidence. PROTAC: ubiquitination databases record sites on it.
Gene: Protein-coding gene on chromosome X (3,308,565 to 3,346,652, reverse strand). Ensembl gene ENSG00000101825.
Subcellular location: Secreted
Subcellular location (Human Protein Atlas): Mitochondria; Predicted to be secreted
Gene Ontology:
Molecular function: extracellular matrix structural constituent
Biological process: response to transforming growth factor beta
Cellular component: extracellular exosome; extracellular matrix; extracellular region; non-collagenous component of interstitial matrix
Homologues: Orthologues: macaque MXRA5 (95% identical), dog MXRA5 (75% identical), tropical clawed frog mxra5 (44% identical), zebrafish si:ch211-159i8.4 (27% identical). Paralogues in human: IGSF10 (29% identical), HMCN2 (16% identical), DSCAM (12% identical), DSCAML1 (12% identical), SDK2 (10% identical), SDK1 (10% identical), ROBO1 (9% identical), NEO1 (8% identical), ROBO3 (8% identical), ROBO2 (8% identical), DCC (8% identical), PTPRQ (8% identical), and 24 more.
Diseases named in the same sentence as MXRA5 in open-access papers:
MXRA5 is named in the same sentence as 61 diseases in open-access papers, as found by Europe PMC text mining. Sharing a sentence is not in itself a finding about the gene and the disease. The quoted sentences say what the papers report.
colorectal cancer (11 papers, 2013 to 2025). A primary or metastatic malignant neoplasm that affects the colon or rectum. "MXRA5 shows substantial expression alterations in multiple tumors, such as colorectal cancer, and is strongly linked to tumor progression, invasion, and prognosis." (PMID 40688463, 2025). "The CpG cg26738106 (MXRA5) was negatively associated with risk of colorectal cancer in our data, but the age-by-sex interaction observed in the set of controls was not replicated in the set of cases and therefore requires further investigation." (PMID 33919912, 2021). "In our previous study, significantly high expression levels of matrix-remodeling associated 5 (MXRA5) were identified in fresh-cultured colorectal cancer (CRC) tissues compared with their normal adjacent mucosa by differential secretome analysis." (PMID 23420087, 2013). "Matrix-remodeling associated 5 protein, which is encoded by MXRA5, is a novel biomarker in colorectal cancer and non-small-cell lung carcinoma." (PMID 34249924, 2021). "MXRA5, a matrix-remodeling protein, was identified as a colorectal cancer biomarker and was also found to be downregulated in GCA." (PMID 34804955, 2021). "MXRA5 has been reported to be a novel biomarker which is upregulated in non–small cell lung carcinoma and colorectal cancer." (PMID 32392178, 2020). "MXRA5 is a cancer related gene and several studies indicated the potential value of this gene as a novel therapeutic target for various cancers including colorectal cancer, non-small cell lung cancer and glioblastoma multiform." (PMID 32620106, 2020). "Somatic mutations of MXRA5 are observed in patients with non-small cell lung cancer (NSCLC), MXRA5 is also aberrantly expressed in colorectal cancer (CRC) tissues, serving as a critical biomarker for the diagnosis and prevention of CRC." (PMID 32392178, 2020). "As MXRA5 is overexpressed in ovarian, lung and colorectal cancer 24, 25, 26, we studied MXRA5 expression in VHL‐defective ccRCC cell line (VHL−/−)." (PMID 27599751, 2017). "MXRA5 was proposed as a novel biomarker in colorectal cancer 26, as it was overexpressed in colorectal cancer tissue compared with their corresponding normal tissue." (PMID 27599751, 2017). "DSCC1 is more upregulated in GCA than colorectal adenocarcinoma; KCNQ1OT1 and MXRA5 are downregulated in GCA, compared to other colorectal cancers." (PMID 40729214, 2024). "Studies have reported MXRA5 upregulation in human malignancies, including non-small cell lung cancer (NSCLC), colorectal cancer (CRC), and glioma." (PMID 36828810, 2023). "MXRA5 could be important for the tumorigenesis and progression of human cancer, including non-small cell lung cancer (NSCLC), colorectal cancer, breast cancer and glioma." (PMID 36828810, 2023).
non-small cell lung carcinoma (9 papers, 2018 to 2024). A group of at least three distinct histological types of lung cancer, including non-small cell squamous cell carcinoma, adenocarcinoma, and large cell carcinoma. "MXRA5 was identified to be frequently mutated in non-small cell lung carcinoma and the high MXRA5 expression was correlated with tumor progression." (PMID 35752862, 2022). "For instance, somatic mutations of MXRA5 are observed in patients with non-small-cell lung cancer (NSCLC)." (PMID 34211612, 2021). "Somatic mutations in MXRA5 have been observed in non-small-cell lung carcinoma patients." (PMID 39513108, 2024). "Among the hubs of the 6 modules, 5 of them (PTPN22, BRIP1, CEACAM6, LTF, and CCNT1) have been previously found to be associated with breast cancer, and the other one, MXRA5, has been reported to be related to non-small cell lung cancer." (PMID 30240439, 2018). "Indeed, MXRA5 has been shown to be a target of TGF involved in the regulation of inflammation and fibrosis in chronical diseases and it has been suggested as prognostic biomarker in colorectal and non-small cell lung cancer." (PMID 32872534, 2020).
breast carcinoma (6 papers, 2016 to 2024). "MXRA5 is also upregulated in breast cancer and was found to be important for the EMT progression and matrix remodeling." (PMID 39149564, 2024).
glioma (6 papers, 2021 to 2025). A benign or malignant brain and spinal cord tumor that arises from glial cells (astrocytes, oligodendrocytes, ependymal cells). "We also explored the relationship between MXRA5 mRNA expression level and IDH mutation status and found that MXRA5 was highly expressed in IDH wild-type glioma in both the CGGA and TCGA datasets." (PMID 34211612, 2021). "Our study suggests that MXRA5 expression is associated with the clinicopathologic features and poor prognosis of gliomas." (PMID 34211612, 2021). "MXRA5 exhibits anti-inflammatory and anti-fibrotic properties and has been implicated in tumorigenesis, serving as a potential biomarker for multiple malignancies, including colorectal, lung, pancreatic, and gastric cancers, as well as glioma and acute myeloid leukemia." (PMID 40429753, 2025). "We analyzed the clinical and molecular characteristics as well as the prognostic value of MXRA5 in glioma." (PMID 34211612, 2021). "This is the first integrative study molecularly and clinically characterizing MXRA5 expression in whole WHO-graded gliomas." (PMID 34211612, 2021). "Analysis of clinical survival data also confirmed that the survival time of glioma patients with high expression of MXRA5 was significantly shorter than that of patients with low expression." (PMID 34211612, 2021). "As a secreted glycoprotein, MXRA5 is a potential circulating biomarker for glioma, deserving further investigation." (PMID 34211612, 2021). "We found that MXRA5 expression was significantly upregulated in high-grade gliomas and IDH wild-type gliomas compared to controls." (PMID 34211612, 2021). "To further analyze the prognostic value of MXRA5, we divided glioma patients into the MXRA5 high-expression group and low-expression group based on the MXRA5 mRNA expression level (median)." (PMID 34211612, 2021). "Our results suggest that MXRA5 is more highly expressed in IDH wild-type glioma, which indirectly suggests that MXRA5 is more highly expressed in glioma with poor prognosis." (PMID 34211612, 2021). "To further verify the expression level of MXRA5 in glioma cell lines, we performed RT-qPCR with A172 cells and TJ905 cells." (PMID 34211612, 2021). "In glioma and many malignancies, MXRA5 is more highly expressed in tumor tissues than in normal tissues." (PMID 34211612, 2021). "To further investigate the role of MXRA5 in the glioma immune microenvironment, we performed Pearson correlation analysis of key markers of TAMs and Treg cells." (PMID 34211612, 2021). "We found that MXRA5 mRNA and protein expression was upregulated in glioma, especially GBM, and was an unfavorable prognostic biomarker for patients with glioma." (PMID 34211612, 2021). "High MXRA5 expression could be used as an independent indicator of poor prognosis in glioma patients." (PMID 34211612, 2021). "We will continue to explore the molecular mechanism by which MXRA5 influences glioma biology." (PMID 34211612, 2021). "MXRA5 mRNA expression was analyzed according to the WHO grading system in glioma." (PMID 34211612, 2021). "We found that MXRA5 expression was higher in glioma than in most other cancers." (PMID 34211612, 2021). "Furthermore, univariate and multivariate Cox regression hazard analyses showed that the MXRA5 mRNA expression level was an independent prognostic factor for glioma (p = 0.018)." (PMID 34211612, 2021). "These analyses indicate that the biological function of MXRA5 may be related to tumor invasion and the immune microenvironment of glioma." (PMID 34211612, 2021). "Therefore, in the present study, we aimed to conduct a comprehensive analysis to explore the molecular and clinical characteristics of MXRA5 in glioma." (PMID 34211612, 2021). "High MXRA5 expression might act as an independent signal of a bad prognosis in glioma." (PMID 38152333, 2023). "In addition, the role of MXRA5 in glioma was only preliminarily speculated through bioinformatics analysis." (PMID 34211612, 2021).
glioma (continued). "In addition, IDH wild-type glioma may also regulate the occurrence and progression of the tumor through the MXRA5 pathway, leading to poor prognosis." (PMID 34211612, 2021). "MXRA5 may play an important role in the immunosuppressive microenvironment of glioma." (PMID 34211612, 2021). "To further characterize the relationship of MXRA5 expression level and tumor specimens, we measured the MXRA5 protein level in glioma tissue samples from twenty-eight patients (1 with grade I glioma, 7 with grade II glioma, 7 with grade III glioma, and 13 with GBM) using IHC analysis." (PMID 34211612, 2021). "However, little information is available concerning MXRA5 expression in glioma." (PMID 34211612, 2021). "To further explore the role of MHC in gliomas, we used LASSO regression analysis and identified four genes (TNFSF14, MXRA5, FCGR2B, and TNFRSF9) related to the major histocompatibility complex (MHC)." (PMID 40429753, 2025). "Using WGCNA and LASSO algorithms, we identified four MHC-related genes (TNFSF14, MXRA5, FCGR2B, and TNFRSF9) as prognostic biomarkers for glioma." (PMID 40429753, 2025). "To further verify the correlations of PD-L1 with FMOD, MXRA5 and RAB36, we established a mouse model using CT2A and GL261 mouse glioma cells." (PMID 39513108, 2024). "In the present study, we found that MXRA5 mRNA and protein expression was closely related to tumor grade, with the highest expression in GBM among other glioma subtypes, and the expression in mesenchymal-subtype GBM was higher than that in other subtypes." (PMID 34211612, 2021). "However, the prognostic value and role of MXRA5 in glioma remain unclear." (PMID 34211612, 2021). "However, the role and mechanism of action of MXRA5 in gliomas remain unclear." (PMID 34211612, 2021). "MXRA5 mRNA expression was upregulated in GBM compared to lower-grade gliomas (LGG), which was verified by RT-qPCR in twenty-eight glioma samples from Tianjin Medical University General Hospital." (PMID 34211612, 2021). "However, the specific mechanism by which MXRA5 mediates glioma development remains unclear." (PMID 34211612, 2021). "Additionally, Cox univariate and multivariate analyses of MXRA5 expression and clinicopathological features revealed that MXRA5 expression has a correlation with age and WHO pathological stage, suggesting that MXRA5 could be an independent prognostic factor for glioma patients." (PMID 34211612, 2021).
lung cancer (5 papers, 2016 to 2023). A malignant neoplasm involving the lung. "Besides MPM, mutations in MXRA5 were previously reported in liposarcoma, colon and lung cancer." (PMID 32872534, 2020). "COL5A2, MXRA5, and VCAN coexpressed with THBS2 may have significant oncogenic functions in both breast and lung cancers." (PMID 27513329, 2016).
aortic stenosis (4 papers, 2022 to 2024). Aortic valve stenosis is a aortic valve disease caused by the incomplete opening of the aortic valve. "It is worth noting that MXRA5 plays an anti-fibrotic role in the pathological process of aortic stenosis, which needs to be confirmed by further studies." (PMID 39749331, 2024). "Among these upregulated genes, FNDC1 and MXRA5 have been recently reported as signatures of chondrocyte-mediated valve calcification in aortic stenosis." (PMID 36548025, 2022). "Notably, MXRA5 plays an anti-fibrotic role in the pathological process of aortic stenosis, although further studies are needed for confirmation." (PMID 39749331, 2024). "Both FNDC1 and MXRA5 have been identified as novel extracellular matrix (ECM) biomarkers in calcified valves, making them potential targets in the development and progression of aortic stenosis." (PMID 38077583, 2023).
glioblastoma multiforme (4 papers, 2020 to 2023). "The ROC findings found that MXRA5 has the potential to function as an indicator for the mesenchymal subtype of glioblastoma multiforme." (PMID 38152333, 2023). "Receiver operating characteristic (ROC) analysis showed that MXRA5 is a potential marker of the mesenchymal subtype of glioblastoma multiforme (GBM)." (PMID 34211612, 2021). "However, in glioblastoma, MXRA5 mutations do not significantly alter prognosis." (PMID 35292033, 2022).
heart failure (3 papers, 2022 to 2025). Inability of the heart to pump blood at an adequate rate to meet tissue metabolic requirements. "We screened for differentially expressed genes in heart failure using available gene expression data from the Gene Expression Omnibus database and identified 6 important genes by a random forest classifier (ASPN, MXRA5, LUM, GLUL, CNN1, and SERPINA3)." (PMID 36254001, 2022).
osteoarthritis (3 papers, 2013 to 2021). A noninflammatory degenerative joint disease occurring chiefly in older persons, characterized by degeneration of the articular cartilage, hypertrophy of bone at the margins and changes in the synovial membrane. "Some of them, including MXRA5 (Chemerin), have been previously associated with osteoarthritis, and anti-inflammatory and anti-fibrotic properties have been proposed for this protein suggesting its potential role in chronic inflammation." (PMID 34200627, 2021). "MXRA5 is an adhesion proteoglycan with VEGF receptor activity that shows elevated expression in the cartilage of patients with osteoarthritis, and is involved in adhesion and matrix remodeling." (PMID 23420087, 2013). "MXRA5, a secreted adhesion proteoglycan with VEGF receptor activity, is elevated in the cartilage of patients with osteoarthritis and can be detected in synovial fluid." (PMID 34211612, 2021).
ovarian carcinoma (3 papers, 2013 to 2023). A malignant neoplasm originating from the surface ovarian epithelium. "MXRA5 was found overexpressed in ovarian cancer compared with normal ovaries and it was involved in tumour angiogenesis." (PMID 27599751, 2017).
pancreatic cancer (3 papers, 2023 to 2024). "Here bioinformatics studies and protein chip analyses of MXRA5-overexpressed pancreatic cancer cells revealed that MXRA5-associated DEGs and differentially DEPs are both enriched in PI3K-Akt-mTOR cascade." (PMID 36828810, 2023). "Here we examined expression, potential functions and underlying mechanisms of MXRA5 (matrix remodeling associated 5) in pancreatic cancer." (PMID 36828810, 2023). "Here, we tested the expression, potential functions and underlying molecular mechanisms of MXRA5 in pancreatic cancer." (PMID 36828810, 2023). "Moreover, intratumoral injection of adeno-associated virus-packed MXRA5 shRNA potently inhibited primary pancreatic cancer cell growth in nude mice." (PMID 36828810, 2023). "Bioinformatics studies and protein chip analyses identified an association between overexpressed MXRA5 and PI3K-Akt-mTOR cascade in pancreatic cancer cells." (PMID 39149564, 2024). "Collectively, MXRA5 shRNA resulted in robust anti-pancreatic cancer cell activity, inhibiting cell viability, proliferation, cell cycle progression and motility." (PMID 36828810, 2023). "As shown, in pancreatic cancer tissues MXRA5 is co-expressed with a number of key ECM-TFs, including Zeb1, Zeb2, Twist and Slug." (PMID 36828810, 2023). "MXRA5 shRNA/KO inhibited pancreatic cancer proliferation, cell cycle progression, and mobility, we next tested its potential activity on cell apoptosis." (PMID 36828810, 2023). "The number of MXRA5 transcripts in pancreatic cancer tissues is significantly higher than that in the normal pancreatic tissues (P < 0.001)." (PMID 36828810, 2023). "ROC curves were applied to verify the accuracy of the model according to MXRA5 expression in pancreatic cancer tissues and clinicopathological characteristics of the patients." (PMID 36828810, 2023). "MXRA5 mRNA and protein expression is elevated in microarray pancreatic cancer tissues and various pancreatic cancer cells." (PMID 36828810, 2023). "Together, these results revealed that CRISPR/Cas9-induced MXRA5 KO induced potent anti-pancreatic cancer cell activity." (PMID 36828810, 2023). "The representative immunohistochemistry (IHC) images of six patients (“Patient 1#” and “Patient 6#”) demonstrated that MXRA5 protein expression in the pancreatic cancer tissues (“Ca”) was higher than that in the paracancer pancreatic tissues (“ParaCa”)." (PMID 36828810, 2023). "As shown, MXRA5 mRNA expression in pancreatic cancer tissues (“Ca”) was again significantly higher than that in paracancer tissues (“ParaCa”)." (PMID 36828810, 2023). "The bioinformatics studies revealed that MXRA5 transcripts are significantly elevated in pancreatic cancer tissues, correlating with the poor overall survival, high T-stage, N1 and pathologic stage." (PMID 36828810, 2023). "After combining all 16 pairs of blotting data, results showed that MXRA5 protein upregulation in pancreatic cancer tissues was significant (P < 0.05 vs. “PareCa” tissues)." (PMID 36828810, 2023). "Kaplan-Meier survival plus univariate Cox analysis confirmed that high MXRA5 expression in pancreatic cancer was correlated with the poor prognosis of the patients." (PMID 36828810, 2023). "In primary and established pancreatic cancer cells, MXRA5 depletion, using shRNA or CRISPR/Cas9 strategies, robustly suppressed cell viability, cell cycle progression, proliferation and motility, while provoking apoptosis." (PMID 36828810, 2023). "As shown, the number of MXRA5 transcripts in pancreatic cancer tissues is significantly higher than that in the normal pancreatic tissues (Fold change = 5.430, P = 2.17E-15)." (PMID 36828810, 2023). "MXRA5 mRNA and protein expression is significantly elevated in microarray pancreatic cancer tissues and different pancreatic cancer cells." (PMID 36828810, 2023).